NDRG1 (N-myc downstream regulated 1)
Diseases named in the same sentence as NDRG1 in open-access papers (continued):
Sharing a sentence is not in itself a finding about the gene and the disease.
tumor (continued). "Further studying NDRG1 expression in BCa xenografts and PDX tumours showed that depleting NDRG1 resulted in a decrease in migration, colony formation, invasion, and tumour initiating cells in the aggressive ER-negative BCa cells in vitro and in vivo." (PMID 36497221, 2022). "The mRNA expression of NDRG1 and NDRG2 was found to be significantly different (P <0.001) in almost all tumor types, including LIHC." (PMID 35795037, 2022). "The multivariate regression analysis showed that EZH2, NDRG1 and GRPEL2, as well as the tumor size were independent factors for the prognosis of HCC." (PMID 36686830, 2022). "Analysis of their expression levels in tumor patients and normal subjects identified five core prognostic markers, which were EIF4EBP1, BCL2A1, NDRG1, ERRFI1 and BRD4." (PMID 36524001, 2022). "Compared with normal tissues, NDRG1 expression was higher, whereas NDRG2 expression was lower in tumor tissues (P <0.001)." (PMID 35795037, 2022). "Tumor TNM stage and age, as well as the expression level of NDRG1 or NDRG2, were included in the nomogram to predict OS (C-index: 0.676), DSS (C-index: 0.741) and PFI (C-index: 0.630)." (PMID 35795037, 2022). "NDRG1, BHLHE40 and VEGFA, which were found in tumour cluster B, mainly affect tumour proliferation, metastasis and invasion." (PMID 35109839, 2022). "Specifically, in the tumour region, we observed enrichment of PPIB and UGT2B15 and IFI27, NDRG1, BHLHE40 and VEGFA." (PMID 35109839, 2022). "The results showed that the transcriptional expression levels of NDRG1 (P < 0.001), ERRFI1 (P < 0.001), IRS2 (P < 0.001), IGFBP4 (P < 0.01), and BIRC3 (P < 0.01) were significantly decreased in tumor tissues, while SOCS1 (P < 0.05) expression was increased." (PMID 35859293, 2022). "In our previous study, NDRG1 was remarkably reduced in CRC tissues and was negatively correlated with tumor stage and metastasis." (PMID 33994856, 2021). "However, other studies implied that NDRG1 may functions in tumour microenvironment remodelling." (PMID 34965023, 2021). "For example, N-myc downstream regulated gene 1 (NDRG1)/Cap43 downregulates the expression of CXCL1, CXCL5, CXCL8, and VEGF in tumor cells, leading to the suppression of neutrophil infiltration." (PMID 34439836, 2021). "Since the first characterization of NDRG1 in 1999, the NDRG family has been reported to play promiscuous roles in tumorigenesis or tumor suppression." (PMID 31935861, 2020). "Elevated NDRG1 expression was observed in HCC and dramatically related to overall survival and tumor stage." (PMID 32046766, 2020). "In the high NDRG1 group of biopsy specimens before NAC, the tumor reduction rate by NAC was significantly attenuated (P = 0.021)." (PMID 32106831, 2020). "More specific, ADM, NDRG1, and TUBB6 were down-regulated, while other 10 genes were up-regulated in tumor samples compared with normal control." (PMID 33344235, 2020). "Similar to HCT116 cells, when NDRG1 was silenced in SW1116 cells, the tumor weight and volume dramatically increased compared to the relative control group (1292 ± 110.6 vs. 329.4 ± 72.72 mg, p < 0.0001) and (3247 ± 353.2 vs. 690.4 ± 201.6 mm3, p < 0.001)." (PMID 31831018, 2019). "The balance between these two critical cell growth regulators in RMS has a profound impact on tumor cell growth and apoptosis through co-regulation of essential cell growth and cell cycle control genes such as CDKN1A (p21), PTEN, NDRG1 and CST6." (PMID 29719592, 2018). "As we knocked down NDRG1 in TW04 cells, the cell proliferative rate increased, indicating NDRG1 is also a tumor suppressor gene in NPC cell, compatible with the previous study." (PMID 29738439, 2018). "NDRG1 and NDRG2, which have been well reported as tumor suppressors for oral and esophageal squamous carcinoma." (PMID 29738439, 2018).
tumor (continued). "Results showed that DpdtC exerted the potent anti-tumor effects against HER2-overexpressed SK-OV-3 and SK-BR-3 cells, especially on SK-OV-3 cells with a higher NDRG1 level, which was also confirmed in the SK-OV-3 xenograft model." (PMID 29467385, 2018). "To conclude, our results showed that both NDRG1 overexpression and treatment with DpdtC caused significant inhibitory effect on HER2/EGFR heterodimer formation and ERK1/2 activation, which may be a novel mechanism involved in the potent anti-tumor activity of DpdtC." (PMID 29467385, 2018). "Increased CSTB and NDRG1 expression was identified in the inner tumor, according to the MS discovery results, with staining only inside neoplastic cells of the OSCC, but in some cases, CSTB and NDRG1 were also detected in the adjacent normal epithelium." (PMID 30185791, 2018). "In summary, for the first time, our study provides valuable insight into the anti-tumour mechanism of rGal3C involving integrin/FAK/SRC pathway and NDRG1 in HCC on a proteomics level." (PMID 28701735, 2017). "Our results suggested the possible anti-tumour mechanism of rGal3C in HCC involved in Integrin/FAK/SRC pathway and NDRG1." (PMID 28701735, 2017). "Our study provides valuable insight into the anti-tumour mechanism of rGal3C in HCC on a proteomics level and is the first to reveal the possible mechanism involving integrin/FAK/SRC pathway and NDRG1." (PMID 28701735, 2017). "We showed for the first time that the N-myc downstream regulated gene 1 (NDRG1) and NDRG2, known as tumor suppressor genes, are negatively regulated by LCN2 in CCA cells." (PMID 27782193, 2016). "In contrast, excess FtMt significantly upregulated NDRG1 in SH-SY5Y cells, indicating that FtMt can have some effect on tumor cell growth and metastasis." (PMID 25213357, 2015). "In vivo, we consistently observed that NDRG1 suppression in HCC xenografts decreased β-catenin levels and its downstream target Cyclin D1, with concomitant tumor growth inhibition." (PMID 26359353, 2015). "Using Co-IP, we detected NDRG1-GSK-3β and NDRG1-Nur77 interaction complexes in tumor lysates of control groups from both Hep3B and HepG2 xenografts, but not in their respective NDRG1 shRNA groups." (PMID 26359353, 2015). "Furthermore, the reported tumor-promoting role of NDRG1 and the role in metastasis suppression, which are apparently contradictory may be explained by involvement of NDRG1 both in cell survival under hypoxia and in doxorubicin-induced apoptosis under normoxia." (PMID 24498060, 2014). "Comparing to the level of NDRG1 in the non-tumor tissues, 8 CRC tissues showed a significant reduction of NDRG1 (p<0.001–0.01)." (PMID 23874544, 2013). "The RT-qPCR analyses showed that expression from NDRG1, MASPIN, and KAI1 genes was significantly increased in the HT-IL6 xenograft tumor cells compared with HT-DNA xenograft tumor cells." (PMID 23762858, 2013). "In this study, the expression of NDRG1 and its clinicopathological significances were investigated in 240 CRC specimens and their paired non-tumor counterparts." (PMID 23874544, 2013). "N-myc downstream regulated gene 1 (NDRG1) belongs to the NDRG family, and its expression has been shown to be negatively correlated with tumor metastasis." (PMID 23762858, 2013). "IHC staining indicated that NDRG1 was predominantly presented in the cytoplasm in CRC cells and normal cells in the paired non-tumor colorectal tissues." (PMID 23874544, 2013). "Importantly, restoration of NDRG1 expression rescued the NB cells from FOXD3-mediated suppressive phenotypes in growth, aggressiveness and angiogenesis, suggesting that FOXD3 may exert its tumor suppressive function, at least in part, through transcriptional regulation of NDRG1 in NB." (PMID 24269992, 2013). "Recent findings have demonstrated that NDRG1 interacts with the Wnt receptor, LRP6, blocking Wnt signaling and impairing the metastatic progression of tumor cells in prostate and breast cancer." (PMID 24260043, 2013).
tumor (continued). "NDRG1 expression was also analyzed by immunoblot in 10 CRC tumors at stage III-IV and 10 paired non-tumor tissues." (PMID 23874544, 2013). "Whereas Panc-1, the more aggressive undifferentiated cell line, showed a modest increase of NDRG1 mRNA or protein under different HIF-1α stabilizer, compared to the prominent response of the moderately differentiated tumour cell line, Capan-1." (PMID 16832411, 2006). "In addition, it has been reported that Ndrg1 is directly or indirectly regulated by HIF-1α in an oxygen-dependent manner, thereby affecting cancer metabolism and tumor progression." (PMID 40484376, 2025). "The FOXQ1/NDRG1 axis promotes the initiation of HCC by modulating the crosstalk between CAFs and tumor cells, which forms a circular reinforcement loop to attract HSCs and encourage tumor proliferation." (PMID 40755769, 2025). "Collectively, these findings highlight the critical role of NDRG1 in orchestrating an immunosuppressive TME by driving lactate accumulation, promoting M2 macrophage polarization, and inhibiting CD8+ T cell function, thereby facilitating tumor progression." (PMID 40539245, 2025). "In these studies, NDRG1 mRNA expression was higher in tumor tissues compared to normal tissue and also in higher ER-negative tumors relative to ER-positive tumors." (PMID 40378957, 2025). "Univariate and multivariate analyses showed that NDRG1 and RBP7 were independent prognostic factors for OS, and RBP7 might act as a tumor suppressor gene in hormone receptor-positive breast cancer." (PMID 38553715, 2024). "Conversely, NDRG1‐negative cases exhibited significantly reduced survival outcomes compared with NDRG1 low tumours (p = 0.015)." (PMID 40530439, 2024). "N-myc downstream–regulated gene 1 (NDRG1) is a protein that can modulate tumor angiogenesis; however, its role in regulating tumor angiogenesis and VM formation has not been previously investigated in UC." (PMID 38561462, 2024). "Furthermore, the increased expression of Cdx2, and other differentiation-driving transcription factors like Klf4 and the WNT antagonist, Ndrg1, in BLM tumors push the tumor stem cells toward the various differentiated lineages." (PMID 38893159, 2024). "To further delineate the crucial target gene, we initially conducted a comparative analysis of SPP1, NDRG1, SFN and LDHA mRNA expression levels in clinical samples of HCC and adjacent non-tumor tissues, as well as various HCC cell lines and normal liver cell lines." (PMID 39066845, 2024). "Interestingly, Ndrg1 had high velocity in the tumor stem cells of BLM tumors, while in Min tumors, Ndrg1 only started to show velocity in differentiated enterocytes and goblet cells (Velocity)." (PMID 38893159, 2024). "No survival advantage was observed for NDRG1‐low tumours in the HER2+ or TNBC group; however, NDRG1‐low tumours in the ER+ group showed a significantly improved BCSS." (PMID 40530439, 2024). "Ndrg1 showed high-velocity expression in the tumor stem cell population of BLM tumors, while it was absent in Min tumor stem cells." (PMID 38893159, 2024). "In tumor cells, MALAT1 facilitates EZH2-binding to its target loci, driving H3K27 trimethylation-mediated repression of multiple tumor-suppressor genes, such as E-cadherin, NDRG1, p21, and p27." (PMID 37048060, 2023). "Our results showed that TGFβRI and GSK3β are located upstream of NDRG1 in the signaling pathway and demonstrated that a combination of TGFβ and GSK3β inhibitors has the potential to reduce TNBC progression by impairing tumor initiation and ALDH1+ and CD44high/CD24- populations of CSCs." (PMID 36594086, 2023). "Only the expressions of ERRFI1, ETS1, NDRG1, and ZMAT3 were detected in the tumor microenvironment." (PMID 37600707, 2023). "Future studies investigating whether NDRG1 might differentially influence the different CAF sub-types, and the functional consequences in terms of tumor progression are required to further establish the therapeutic potential of this metastasis suppressor." (PMID 37345116, 2023).
tumor (continued). "Because we found that NDRG1 and its phosphorylation at Thr346 were altered by TGFβ1, we next tested whether their expression levels were correlated in TNBC patient tumor tissue." (PMID 36594086, 2023). "Notably, IL1B, NDRG1 and TIMP1 act as drivers of ferroptosis, and their low expression in patients with poor prognosis implies a correlation between tumor cell resistance to ferroptosis mechanisms and poor prognosis." (PMID 36226170, 2022). "Further investigations on clinical tissue and peritoneal dissemination model of nude mice also indicated that CDC42GTP expression has a negative correlation with NDRG1 expression in CRC tissues and is associated with the advanced invasiveness of the tumor." (PMID 33994856, 2021). "Therefore, NDRG1 inhibits the pro-oncogenic and survival activity of the PI3K/AKT pathway in cancer, suppressing tumor growth and metastasis." (PMID 34572031, 2021). "Although tumor growth was partially limited by CTX in NDRG1-knockdown cells, this tendency of increased growth was not dramatically reversed." (PMID 34385595, 2021). "Not surprisingly, the bioluminescent imaging showed the tumor burdens of the sh-NDRG1 group were more massive than that of controls in the peritoneum of hosts (P<0.01)." (PMID 33994856, 2021). "And the mRNA level of NDRG1 from tumour tissues was higher than that from normal renal tissues (normal: n = 72, tumour: n = 530) (P < .0001)." (PMID 32537867, 2020). "Results from our present study indicate that NDRG1 was activated via Sgk1 in ESCC undergoing NAC and thus could be involved in the local progression of the tumor." (PMID 32106831, 2020). "The low expression of NDRG1 was accompanied by low protein levels of HIF‐1α and 2α in IHC images of tumour tissues from Patient I. Moderate and high protein levels of HIF‐1α and 2α correspond to moderate and high NDRG1 expression, respectively, from Patients II and III." (PMID 32537867, 2020). "There were convincing proofs that over-activation of HIF-1 could lead to aggressive proliferation and invasion of tumor cells, which was achieved via alteration of MMP9, VEGF and NDRG1 expressions." (PMID 32143722, 2020). "In addition, the Wnt pathway was also reported to be activated via NDRG1 and involved in epithelial-mesenchymal transition of ESCC tumor cells." (PMID 32106831, 2020). "In addition, NDRG1 was shown to be down‐regulated by VHL and involved in carcinoma, apoptosis, cell death and migration of tumour cell lines." (PMID 32537867, 2020). "To further determine whether p21 was responsible for the changes in tumor growth regulated by NDRG1, we constructed stably transfected SW1116 cell lines with p21 overexpression after NDRG1 was knocked down (SH-NDRG1/p21)." (PMID 31831018, 2019). "Likewise, the FOXQ1/NDRG1 axis was shown to exacerbate HCC initiation via enhancing cross talk between fibroblasts and tumor cells, and FOXO1 was reported to contribute to HCC through a different mode of action." (PMID 31615920, 2019). "In CRC patients, NDRG1 expression was found to be an independent prognostic factor for survival and tumor recurrence: CRC patients that are NDRG1 negative face a worse prognosis in cancer-free and overall survival." (PMID 31641356, 2019). "This study reported a significantly lower overall survival in patients with low NDRG1 expression, independent of other prognostic indicators (e.g. tumor grade)." (PMID 31485792, 2019). "NDRG1 was down-regulated in CRC tissues and correlated with tumor size and patient survival." (PMID 31831018, 2019). "Since EMT is a key process for tumor cells to metastasize to other places, adding the finding that TW04-shNDRG1 cells had greater invasive ability than TW04-shCTRL cells, we further evaluated the influence of NDRG1 for EMT-related proteins." (PMID 29738439, 2018).
tumor (continued). "Among them, 13 proteins correlated with clinicopathological parameters and of these proteins, eight proteins were identified in neoplastic islands (ACTR2, CSTB, COL1A2, LTA4H, PGK1, NDRG1, S100A8, S100A9) and five proteins were identified in tumor stroma (COL6A1, FSCN1, ITGAV, MB, THBS2)." (PMID 30185791, 2018). "Our data showed a negative correlation between NDRG1 expression and tumor size, local invasion, lymphatic invasion, and TNM stage." (PMID 29137287, 2017). "NDRG1 is one of the four members of the human NDRG family, and its designation comes from its expression being repressed by MYC and MYCN and its expression is negatively correlated with tumor progression in multiple neoplasms." (PMID 27894074, 2017). "The possible anti-tumour mechanism is that rGal3C disrupts Galectin-3-integrin clustering on the cell surface, resulting in suppression of integrin/FAK/SRC pathway and subsequent down-regulation of NDRG1 expression." (PMID 28701735, 2017). "N-myc downstream-regulated gene 1 (NDRG1) is a member of the NDRG gene family, which is expressed ubiquitously in tissues in response to various stress conditions including cellular differentiation, tumor progression and metastasis, DNA damage and hypoxia." (PMID 28045438, 2017). "Another interesting protein with high expression at the TM is the N-myc downstream-regulated gene 1 (NDRG1 pT346) which is regulated by HIF-1α, stress and growth signals, and may be a marker of tumor progression." (PMID 29142297, 2017). "Because SETDB2 knockdown led to significant inhibition of cell growth, migration and invasion, we further selected six tumor- or differentiation-related genes (WWOX, CADM1/TSLC1, CCDC80, NDRG1, CA9 and FZD9) that have been reported to show altered expression in several cancers including GCs." (PMID 27572307, 2016). "There was no significant (p > 0.05) relationship between NDRG1 expression and other parameters, including: gender, age, or tumor location." (PMID 26418878, 2015). "NDRG1 expression in CRC and non-tumor tissues was examined by IHC and immunoblot." (PMID 23874544, 2013). "In contrast, tumours displaying elevated SGK1 mRNA/protein in which NDRG1 phosphorylation is not suppressed by Akt inhibitors are likely to be more resistant to Akt inhibitors." (PMID 23581296, 2013). "NDRG1, one of the four NDRG family genes, thus shows diverse functions, and NDRG1 functions either as metastasis suppressor or as oncogenic and malignant promoter, depending on tumor types." (PMID 22844455, 2012). "The tumor promoting effect of the HCV transgene may be explained both by upregulation of pro-tumorigenic genes as Ubd, Erbb4, Nrg1, Ndrg1, Styk1, and by evasion of host defense response by viral proteins." (PMID 19340302, 2009). "From a clinical point of view, the observed presence of NDRG1 in nontumoral tissue taken together with its negligible expression in undifferentiated tumours argues against its value as a reliable tumour marker." (PMID 16832411, 2006). "In all the samples, NDRG1 staining was restricted to the tumour epithelial cells and no staining was visible in fibrocytes of the desmoplastic reaction." (PMID 16832411, 2006). "The precise biological function of NDRG1 is still not known, but various studies support its role as a potential tumour suppressor protein." (PMID 16832411, 2006). "The other six genes with more than two-fold upregulation in more than five tumours arrayed were CCNG2 in 30 tumours, NDRG1 in 18 tumours, PFKFB3 in 17 tumours, RNAse4 in 10 tumours, Adrenomedullin (ADM) in eight tumours and Glucose transporter 1 (GLUT-1) in six tumours." (PMID 16052224, 2005). "With these features, Ndrg1 has the capacity of reflecting tumour hypoxia in a broader spectrum than does HIF-1 and could be considered as a better signature for hypoxic tumour cells than HIF-1." (PMID 15341671, 2004).